AFP (alpha fetoprotein)
Diseases named in the same sentence as AFP in open-access papers (continued):
Sharing a sentence is not in itself a finding about the gene and the disease.
tumor (continued). "Additional factors retained in the final Cox model based on the akaike information criteria included serum AFP level (HR = 1.7; 95% CI: 1.2, 2.5; p = 0.007), tumor multiplicity (HR = 1.6; 95% CI: 1.0, 2.5; p = 0.06), and MVI (HR = 1.8; 95% CI: 1.2, 2.7; p = 0.003)." (PMID 39028376, 2025). "By integrating AFP, a well‐established tumor marker with confirmed relevance in AFPGC that reflects immune system dynamics, with NLR, an indicator of systemic inflammation, ANLiM offers a comprehensive view of the tumor's biological aggressiveness and the host's immune response." (PMID 40433893, 2025). "Serum tumor markers were elevated, with AFP exceeding 1000 ng/mL and β-HCG at 401.35 mIU/mL." (PMID 41018086, 2025). "Moreover, it has been stated that AFP provides better prognostic information than tumor diameter and number." (PMID 40709064, 2025). "The levels of blood tumor marker alpha-fetoprotein (AFP) were markedly elevated to 36,971 ng/mL." (PMID 40755645, 2025). "Alpha fetoprotein (AFP) was used as HCC tumor marker, and the staining results revealed that comparable levels of AFP in DEN/CCl4‐treated AlbCre; MCT1 f/f and MCT1 f/f mice, indicating that liver‐specific MCT1 deletion was not sufficient to modify the severity of DEN/CCl4‐induced HCC tumors." (PMID 40743299, 2025). "Moreover, biomarker analysis identified elevated bFGF as associated with both malignancy and poor steroid responsiveness, while other tumor markers (AFP, CYFRA21-1) were occasionally abnormal." (PMID 41210047, 2025). "Moreover, the efficacy of HAIC in reducing the levels of serum tumor markers (AFP and PIVKA II) in HCC was significantly better than that of TACE alone." (PMID 40084258, 2025). "3.Liver transplantation criteria have evolved from restrictive morphologic criteria like the Milan criteria to include biological tumour behaviour considerations, although challenges persist in defining optimal alpha-fetoprotein (AFP) cut-off values and incorporating tumour grading." (PMID 39927143, 2025). "Serum tumor markers, including AFP, CA 19-9, and CEA, were evaluated to aid differential diagnosis." (PMID 40843884, 2025). "HAS is mainly characterized by hepatocyte like differentiation and AFP production in tumor tissue." (PMID 40235542, 2025). "Serum tumor markers such as alpha fetoprotein and carcinoembryonic antigen have no practical diagnostic value for PHNETs." (PMID 40958335, 2025). "A subgroup of TCS patients has stable, moderate AFP elevations unrelated to tumour aetiology." (PMID 39934683, 2025). "Similar to AFP, several pediatric tumor biomarkers exhibit physiological age-related variation." (PMID 41515549, 2025). "Notably, early randomization at week 6 is permitted for patients showing tumor enlargement trends or rising AFP levels, reflecting the importance of biomarker dynamics in identifying high-risk SD patients." (PMID 41463142, 2025). "Even criteria that incorporate biological markers as a proxy for tumor behavior (e.g., alpha-fetoprotein, AFP, or des-gamma carboxyprothrombin, DCP, also known as protein-induced by vitamin K absence/antagonist-II, PIVKA-II) have limited sensitivity and specificity." (PMID 39941867, 2025). "AFP did not correlate with stages of the underlying liver fibrosis, tumor size, and tumor inflammation (p > 0.05 for all)." (PMID 40722778, 2025). "Alphafetoprotein (AFP) is the most widely used serological screening and diagnostic marker for HCC in clinical practice and is particularly accurate in diagnosing HCC when combined with other biomarkers, such as circulating tumor cell (CTC) count." (PMID 41471145, 2025). "Furthermore, given that AFP has been identified as having significant value in tumor immunotherapy, the development of vaccines and CAR T cell therapies targeting AFP should be accelerated." (PMID 40430002, 2025).
tumor (continued). "While alpha-fetoprotein (AFP) serves as a serological biomarker, its limitations are well-documented: low sensitivity (approximately 40% of HCC patients exhibit normal AFP) and susceptibility to non-tumor confounders (e.g., liver regeneration, pregnancy)." (PMID 40977712, 2025). "Plasma tumor biomarker profiling demonstrated AFP positivity in 2 cases, elevated CEA (>7 U/L) in 3 cases, CA125 (>35 U/L) in 1 case, CA19-9 (>37 U/L) in 8 cases, and CA72-4 (>7 U/L) in 1 case, highlighting the heterogeneity of biomarker expression in this resectable CCA population." (PMID 41399682, 2025). "The ASAP model contains only two tumor markers (AFP and PIVKA-II)." (PMID 40708828, 2025). "Furthermore, serum AFP levels improved in 16 patients, with a remarkable decrease observed in those with an initial AFP below 100 ng/mL Tumor control, preserved liver function, and reduced platelet count were commonly observed in this cohort." (PMID 41515610, 2025). "Alpha-fetoprotein (AFP) is a widely used tumor marker for HCC." (PMID 40354349, 2025). "Moreover, AFP and DCP levels can fluctuate based on patient characteristics and AFP expression can be influenced by tumor size." (PMID 39941867, 2025). "CRAFITY adds a tumor burden component (AFP) to inflammation (CRP), improving on single markers." (PMID 40568585, 2025). "According to the log-rank test, the methRisk stratified patients into statistically more distinctive risk groups with higher hazard ratio (HR) and lower p-value (HR = 5.29, 95% CI: 1.44–19.48; P = 0.0055) compared to prior AFP, largest tumor size, and MELD score." (PMID 40279344, 2025). "Monitoring AFP levels is a highly sensitive indicator for tumor recurrence." (PMID 40037273, 2025). "At the stage of intermediate follow-up (3-6 months), attention is turned to detailed tumor assessment, it involves Imaging: MRI or CT every three months for the first six months, monitoring Tumor markers, AFP, CEA, or CA19-9, depending on the type of malignancy." (PMID 41458348, 2025). "Thus, in addition to current strategies that primarily focus on attacking tumor cells expressing AFP, there is a need to develop new anticancer drugs that directly target AFP or its signaling pathways, such as small molecules and engineered antibodies." (PMID 40430002, 2025). "This is supplemented with a combination of serum alpha-fetoprotein (AFP) and certain tumor markers." (PMID 40123907, 2025). "AFP has immunosuppressive activity and is negatively correlated with tumor inflammation in females." (PMID 40722778, 2025). "Additionally, we evaluate the correlation between the six HCC EV specific genes and serum AFP, a well-known marker used for assessing tumor viability." (PMID 40307890, 2025). "From the subgroup analyses, the most favorable outcomes, in terms of survival, were especially noted among those with a significant tumor burden, as evidenced by the presence of PVTT, AFP levels ≥ 400 ng/mL, ≥3 intrahepatic lesions, and a main tumor size ≥ 5 cm." (PMID 40361498, 2025). "At present, the clinical diagnosis of intracranial GCTs relies on a combination of imaging characteristics and the presence of tumor markers, namely alpha-fetoprotein (AFP) and beta subunit of human chorionic gonadotropin (β-HCG), in the serum and/or cerebrospinal fluid (CSF)." (PMID 39959669, 2025). "However, subsequent imaging after the eighth and 12th cycles revealed a marked reduction in both tumor burden and AFP levels, confirming pseudoprogression." (PMID 40726876, 2025). "Furthermore, nomogram models incorporating clinical characteristics like tumor size and alpha-fetoprotein levels have been developed to predict outcomes in patients undergoing chemotherapy." (PMID 40308490, 2025).
tumor (continued). "tumor size (p < 0.001), AFP (p = 0.001), ALT (p = 0.013), AST (p = 0.002), PNI (p = 0.032), preoperative TACE number (p = 0.035), targeted therapy and immunotherapy (p < 0.001), and postoperative TACE (p < 0.001) were included in the multivariable Logistic regression analysis." (PMID 41463179, 2025). "The immunomodulatory effects of PD-1 inhibitors may further suppress AFP-secreting tumor subclones, warranting further investigation." (PMID 40936916, 2025). "Multivariate analysis revealed alpha-fetoprotein ≥500 ng/mL (HR = 1.881, 95% CI: 1.028–3.443, p = 0.04), tumor size (HR = 1.833, 95% CI: 1.010–3.327, p = 0.046) and ATEZO/BEV therapy (HR = 0.604, 95%CI: 0.373–0.977, p = 0.04) were independently associated with OS." (PMID 41411278, 2025). "Combining with these novel methylation markers associated with HCC early recurrence, we successfully established a methylation prediction model to distinguish ER from RF with superior performance compared with some current predictors, including tumor size, AFP, and BCLC." (PMID 40075616, 2025). "After surgery, all tumor markers returned to normal ranges (AFP: 8.39 ng/mL; LDH: 338 U/L)." (PMID 41230344, 2025). "Tumor marker levels were as follows: AFP, 552 ng/mL (normal: <10 ng/mL); protein induced by vitamin K absence-II, 23 mAU/mL (normal: <40 mAU/mL); carcinoembryonic antigen, 23 ng/mL (normal: <5.0 ng/mL); and carbohydrate antigen 19-9, 185 U/mL (normal: <37 U/mL)." (PMID 40657563, 2025). "Notably, commonly used tumor markers such as serum alpha-fetoprotein (AFP) are ineffective in predicting early HCC recurrence." (PMID 41388520, 2025). "Serum tumor markers (alpha-fetoprotein, carcinoembryonic antigen, CA-19-9) may be elevated in some cases and can assist in the assessment and monitoring of the tumor." (PMID 40370896, 2025). "Secondly, in most cases, AFP serves as a key tumor marker for diagnosing HCC." (PMID 41211439, 2025). "Tumor markers (AFP and β‐HCG) were within age‐related, normal reference levels." (PMID 40272823, 2025). "Moreover, several characteristics of liver tumors such as AFP levels (p = 0.873), tumor numbers (p = 0.576), portal vein tumor thrombus (p = 0.869), extrahepatic metastases (p = 0.375), and BCLC stage (p = 0.874) were similar between two groups." (PMID 40308633, 2025). "We speculate that when the tumor size is comparable, elevated AFP levels indicate a high degree of tumor malignancy and poor prognosis." (PMID 40857604, 2025). "This is based on elevated levels of the tumor marker AFP(Alfa-fetoprotein)." (PMID 39911278, 2025). "For diagnosis, recognition of the characteristic glandular morphology (the glandular variant being most common) and immunophenotypic expression of markers such as Sal-like protein 4 (SALL4), alpha-fetoprotein (AFP), and glypican-3 is critical for identifying the yolk sac tumor component." (PMID 41425725, 2025). "Tumor marker analysis indicated a significant decrease in the marker used to distinguish high and low tumor marker groups, with AFP levels significantly decreasing in the high AFP marker group and PIVKA-II levels in the high PIVKA-II marker group." (PMID 40002160, 2025). "However, the extremely high levels of HCC tumor markers (i.e., AFP, AFP-L3, and DCP) supported the clinical diagnosis." (PMID 40696641, 2025). "AFP may serve as a surrogate marker for tumor burden or aggressiveness and has been frequently identified as a significant predictor of survival in HCC patients." (PMID 40075741, 2025). "Standard serum tumor markers, AFP, CA19-9, CA72-4, CA50, and CA242 were also unremarkable." (PMID 40165903, 2025). "In contrast, changes in AFP levels following the first treatment cycle were not strongly associated with tumor recurrence-free survival (RFS)." (PMID 41002319, 2025). "AFP is secreted by tumor cells and is positively correlated with tumor size." (PMID 40857604, 2025). "It is well known that both tumour size and AFP level are HCC biomarkers related to prognosis." (PMID 38886351, 2024).
tumor (continued). "The high-risk group predicted by our model exhibited an unfavorable overall survival (OS) outlook and demonstrated an association with adverse worse clinical characteristics such as larger tumor size, higher alpha-fetoprotein, microvascular invasion and advanced stage." (PMID 38972883, 2024). "Tumor marker tests showed borderline elevated AFP levels of 17.5 ng/ml (normal 0–15 ng/ml)." (PMID 39602931, 2024). "The precise mechanism by which AFP levels influence the efficacy of ICIs in tumor patients remains unclear." (PMID 38408930, 2024). "Finally, our study is the first to perform meta-regression analysis to explore the association between overall survival and local recurrence with multiple covariates such as age, tumor size, total bilirubin, and alpha-fetoprotein." (PMID 38326841, 2024). "Importantly, we demonstrated that circulating K102-Env levels were closely linked to tumor biomarkers CA19-9 and AFP, as well as with advanced cancer in patients with PDAC and HCC." (PMID 39850893, 2024). "AFP and corona enhancement could serve as indicators for tumor load and abnormal venous draining, which showed potential capacity in predicting MVI." (PMID 38886267, 2024). "Furthermore, compared to widely utilized blood tumor markers (such as AFP, CA19-9, CEA, and CA12-5), 1-MNAM demonstrated a more robust association with hepatic functional impairment." (PMID 38890166, 2024). "However, tumor markers alpha-fetoprotein (AFP) (4450 ng/ml), AFPL3 (9.4%), and PIVKA-II (34500 mAU/ml) were elevated." (PMID 39108764, 2024). "AFP is the most widely used tumor marker for diagnosis and evaluation of HCC in clinical practice." (PMID 39165686, 2024). "Based on factors such as tumor size, number, liver function, and alpha-fetoprotein (AFP) level, researchers have developed several prognostic models, including the 6&12 score, HAP score, mHAP score, mHAPII score, mHAPIII score, and the pre-TACE prediction model." (PMID 38448905, 2024). "In the multivariate regression analysis, tumor size (P<0.001), bilobular invasion (P=0.007), high aspartate aminotransferase-to-platelet ratio index (APRI) (P=0.007), and high alpha fetoprotein (AFP) level (P=0.035) were independent risk factors for early TACE refractoriness." (PMID 39258671, 2024). "Tumor markers including alpha-fetoprotein (AFP), human chorionic gonadotropin (hCG), and carcinoembryonic antigen (CEA), as well as inflammatory markers such as C-reactive protein (CRP), procalcitonin (PCT), and interleukin-6 (IL-6), were all within normal ranges." (PMID 38600577, 2024). "Furthermore, increased serum alpha fetoprotein levels, more tumor emboli, advanced clinical phases, larger maximum tumor sizes, and an aggressive histological grade were all associated with TBL1XR1 upregulation in LIHC." (PMID 38347836, 2024). "Elevated levels of tumor markers such as alpha-fetoprotein, carcinoembryonic antigen, CA199, CA125, and CA242 may be observed; however, these markers lack specificity for SPNs." (PMID 38870658, 2024). "For example, it was reported to use AFP levels or a morphologic evaluation to assess tumor biology." (PMID 39269544, 2024). "A cut-off point for tumor volume (37 cm3) and AFP (23 ng/ml) was identified using ROC analysis." (PMID 38689147, 2024). "Tumor size, tumor number, and AFP level were considered as continuous variables in this model." (PMID 38606106, 2024). "The expression of TKT was correlated with tumor size, Edmondson grade, AFP, and overall survival." (PMID 38434975, 2024). "Tumor markers, namely AFP, CEA, and CA19-9, were within normal ranges." (PMID 39063549, 2024). "One reason is that AFP has two basic forms: native AFP (nAFP) and tumor-derived AFP (tAFP)." (PMID 38660138, 2024). "Due to their contribution to oncogenesis through mechanisms such as angiogenesis, metabolism, immune activation, and tumor invasion, miRNAs are thought to serve as useful biomarkers that may be more sensitive and specific than AFP, β-hCG, and LDH." (PMID 39273446, 2024).
tumor (continued). "Approximately 40% of the tumours showed higher AFP expression than the livers of the same animal, which may explain the only partial response rate of the blood AFP levels to the injection of iRGD in these mice." (PMID 38889481, 2024). "Tumor markers (AFP, bHCG, and LDH) should be performed before surgery as they support diagnosis of TGCT and may be indicative of subtype." (PMID 38958901, 2024). "After treatment, the levels of serum carcinoembryonic antigen, alpha-fetoprotein, cancer antigen 125, and carbohydrate antigen 72-4 decreased in both groups, and the observation group showed a greater reduction in these tumor marker levels compared to the control group (P < .05)." (PMID 38215107, 2024). "With an emphasis on alpha-fetoprotein (AFP), Chen and Shi created a continuous flow immunoassay instrument utilizing a piezoelectric quartz crystal sensor for the precise molecular detection of tumor indicators." (PMID 39220594, 2024). "Additionally, higher MTL5 expression was associated with poorer histological differentiation and elevated serum AFP levels, suggesting a role in tumor grade and clinical markers." (PMID 38283987, 2024). "Elevated AFP levels are typically correlated with higher tumor burden and poorer prognosis." (PMID 39767676, 2024). "Thus, this study aims to unravel the intricate regulation of c-Myc and c-Met by AFP, investigating their impact on tumor growth." (PMID 39135041, 2024). "A univariate Cox survival hazard regression model analysis indicates that Child-Pugh classification (P < 0.05), ALBI score (p < 0.05), PVTT (P < 0.001), tumor size (P < 0.001), and AFP levels (p < 0.05) were significant predictive factors for patient survival, and were found to correlate with OS." (PMID 38589828, 2024). "If iRGD would also increase the transport of tumour-released proteins other than AFP into the blood, this may increase the portion of HCCs detectable by the iRGD manoeuvre and broaden the utility of iRGD in tumour detection." (PMID 38889481, 2024). "Furthermore, all tumor markers, including alpha-fetoprotein (AFP), carbohydrate antigen (CA 19-9), and carcinoembryonic antigen (CEA), were within normal ranges." (PMID 38870658, 2024). "However, it is worth noting that among patients with ALBI grade 2 or 3 and the same tumor burden category, there was a significant variation of approximately 10 months in median OS between groups divided by AFP level of 200 ng/mL." (PMID 38606106, 2024). "In addition, the expression of HSF1 was positively correlated with the tumor size and alpha‐fetoprotein (AFP) level." (PMID 39248163, 2024). "Additionally, we identified a significant relationship between early AFP response and early (3 months post-treatment) objective tumor response." (PMID 39767676, 2024). "In addition to the fixed-effects model for analysis of the age and sex, the random-effects model was selected to analyze all other parameter analyses including AFP level, tumor size, and HBV infection." (PMID 38529202, 2024). "Surgery is generally planned based on AFP levels and the reduction in tumor size." (PMID 39590141, 2024). "Additionally, the existing medical evidence has already confirmed that AFP dynamically reflects tumor activity and indirectly reflects the tumor progression capability." (PMID 38717693, 2024). "This may imply AFP reprograms live cells and remodels the extracellular matrix to promote endothelial-to-mesenchymal transition and tumor angiogenesis." (PMID 38660138, 2024). "DEN + HFHC feeding resulted in tumor nodules and high level of AFP in serum and liver." (PMID 38724499, 2024). "Common tumor-specific promoters include alpha-fetoprotein (AFP) and prostate-specific antigen." (PMID 38167076, 2024). "Univariate Cox proportional regression analysis identified various risk factors for OS in the training cohort, including tumor number, size, differentiation, MVI, AFP, GGT, CD34, CD68, CD66b, Treg/CD8, CCR4-T, CCL17-T, CCL17-I, HHLA-2, CD73-T, and CCR4 + CD73 + cells." (PMID 38914802, 2024).